KMT2B (lysine methyltransferase 2B)
Description:
Histone methyltransferase that catalyzes methyl group transfer from S-adenosyl-L-methionine to the epsilon-amino group of 'Lys-4' of histone H3 (H3K4) via a non-processive mechanism. Part of chromatin remodeling machinery predominantly forms H3K4me1 and H3K4me2 methylation marks at active chromatin sites where transcription and DNA repair take place. Likely plays a redundant role with KMT2C in enriching H3K4me1 marks on primed and active enhancer elements. Plays a central role in beta-globin locus transcription regulation by being recruited by NFE2. Plays an important role in controlling bulk H3K4me during oocyte growth and preimplantation development (By similarity). Required during the transcriptionally active period of oocyte growth for the establishment and/or maintenance of bulk H3K4 trimethylation (H3K4me3), global transcriptional silencing that preceeds resumption of meiosis, oocyte survival and normal zygotic genome activation (By similarity).
Synonyms: WBP-7; HRX2; KIAA0304; MLL2; MLL4; TRX2; WBP7; MLL1B; CXXC10; DYT28; MRD68
Tractability: Small molecule: a structure with a bound ligand is known. PROTAC: UniProt records ubiquitination sites on it; ubiquitination databases record sites on it; its protein half-life has been measured.
Target class: Writer; Protein methyltransferase; Epigenetic regulator
Gene: Protein-coding gene on chromosome 19 (35,717,973 to 35,738,880, forward strand). Ensembl gene ENSG00000272333.
Subcellular location: Nucleus
Subcellular location (Human Protein Atlas): Nucleoplasm; Cytosol
Pathways (Reactome):
Gene expression (Transcription): Formation of WDR5-containing histone-modifying complexes; RUNX1 regulates genes involved in megakaryocyte differentiation and platelet function
Signal Transduction: Deactivation of the beta-catenin transactivating complex; Formation of the beta-catenin:TCF transactivating complex
Chromatin organization: PKMTs methylate histone lysines
Gene Ontology:
Molecular function: histone H3K4 methyltransferase activity; histone H3K4 monomethyltransferase activity; protein binding; unmethylated CpG binding; zinc ion binding; DNA binding
Biological process: positive regulation of DNA-templated transcription; chromatin remodeling; regulation of DNA-templated transcription
Cellular component: histone methyltransferase complex; MLL1/2 complex; nucleus; nucleoplasm
Genetic constraint (gnomAD): Loss-of-function variants: 19 observed, 219.71 expected, observed/expected ratio (o/e) 0.0865, 90% interval 0.059 to 0.13. The synonymous counts are far from expectation, so gnomAD's model fits this gene poorly and the ratio says little. Missense variants: 3,044 observed, 3,486.7 expected, observed/expected ratio (o/e) 0.87, 90% interval 0.85 to 0.9. Synonymous variants: 1,677 observed, 1,401 expected, observed/expected ratio (o/e) 1.2, 90% interval 1.15 to 1.25.
Gene-disease validity (ClinGen):
ClinGen rates the evidence that KMT2B causes each of these diseases.
complex neurodevelopmental disorder with motor features (autosomal dominant): Definitive. A complex neurodevelopmental disorder that involves more than one phenotype associated with the central nervous system, including but not limited to intellectual disability, autism, and seizures (epilepsy).
Homologues: Orthologues: chimpanzee KMT2B (99% identical), macaque KMT2B (98% identical), dog KMT2B (93% identical), mouse Kmt2b (91% identical), guinea pig KMT2B (91% identical), rat Kmt2b (90% identical), pig KMT2B (88% identical), rabbit KMT2B (87% identical), Caenorhabditis elegans set-16 (8% identical), Drosophila melanogaster trr (8% identical), Drosophila melanogaster ash1 (7% identical), Drosophila melanogaster Set1 (7% identical), and 16 more. Paralogues in human: KMT2A (39% identical), KMT2C (16% identical), KMT2D (16% identical), SETD1B (13% identical), SETD1A (11% identical), NSD1 (7% identical), ASH1L (7% identical), EHMT1 (7% identical), NSD3 (7% identical), EHMT2 (7% identical), NSD2 (6% identical), SETDB1 (5% identical), and 7 more.
Diseases named in the same sentence as KMT2B in open-access papers:
KMT2B is named in the same sentence as 76 diseases in open-access papers, as found by Europe PMC text mining. Sharing a sentence is not in itself a finding about the gene and the disease. The quoted sentences say what the papers report.
Dystonia (43 papers, 2017 to 2026). An abnormally increased muscular tone that causes fixed abnormal postures. "On the other hand, THAP1- and KMT2B-related disorders represent two prominent examples associated with transcriptional dysregulation that often feature isolated or seemingly isolated dystonia." (PMID 41518464, 2026). "For some genes, specific functional assays have been developed to assess the impact of variants on protein function, such as aberrant CpG methylation serving as a functional readout for evaluating variants in the dystonia gene KMT2B." (PMID 40533913, 2025). "The results revealed a heterozygous variant of uncertain significance (VUS) in the KMT2B gene, and upon correlating this with the clinical presentation, KMT2B dystonia was strongly suggested as the diagnosis." (PMID 40303543, 2025). "Knockout of Kmt2b in mice forebrain results in altered expression in the dorsal dentate gyrus of a number of genes associated with dystonia including PRKRA and ADCY5." (PMID 39990802, 2025). "The clinical phenotype associated with KMT2B-related dystonia shares significant overlap with the presentation of DYT-TOR1A." (PMID 40724495, 2025). "Review of this extended cohort (n = 133) has enabled us to better delineate the spectrum of clinical symptoms, determine the incidence of dystonia-associated phenotypes, and further understand the types of mutations observed in KMT2B-related disease." (PMID 39990802, 2025). "As information provided in existing literature, this patient exhibits several hallmark features of KMT2B-related dystonia, including motor impairments, intellectual disability, and developmental delay." (PMID 40303543, 2025). "One study included 18 patients with dystonia related to KMT2B mutations and reported greater improvements in motor function in patients with trunk and cervical dystonia, with less clinical impact in patients with laryngeal dystonia." (PMID 38922176, 2024). "In the newly diagnosed patients we confirmed the association between DNA methylation aberration and age at onset of KMT2B-deficient dystonia." (PMID 37365401, 2023). "In contrast, a subset of non-dystonia patients with mutations in MLL2/KMT2B presented with neurodevelopmental delay, ID, microcephaly, short stature, and facial dysmorphic features." (PMID 36845425, 2023). "We previously found evidence of allelic series in KMT2B-associated dystonia where the age of dystonia-onset was associated with the degree of KMT2B-deficient methylation deviation." (PMID 37365401, 2023). "In this report, we present 12 subjects from five unrelated families carrying four rare functionally relevant KMT2B missense variants, identified by a virtual dystonia gene panel derived from WES data." (PMID 36483457, 2022). "The present DNAm analyses confirm the differential behaviour of the identified missense KMT2B variants associated with late-onset dystonia, although they provide evidence of a distinctive DNAm pattern, which suggests their functional and clinical relevance." (PMID 36483457, 2022). "Heterozygous variants in the KMT2B gene are emerging as one of the commonest causes of early onset dystonia, with a caudocranial pattern evolving into generalized dystonia." (PMID 33488508, 2020). "As a possible explanation of this difference, there may be interneuronal redundancy in suppression of KMT2B-deficient dystonia so that mosaics rarely develop dystonia." (PMID 37365401, 2023). "These four cases included an adult patient with isolated focal cervical dystonia as the only symptom, highlighting the possibility that moderate KMT2B-deficiency may play a causative role in a set of dystonia patients much larger than previously thought." (PMID 37365401, 2023). "We now confirmed this association in independent samples of KMT2B-deficient dystonia." (PMID 37365401, 2023). "Three out of 10 patients (with GNAO1, ACTB and KMT2B variants) could be considered for surgical interventions when medical therapies for dystonia fail." (PMID 33446253, 2021).
Dystonia (continued). "Of note, while KMT2B was identified as a dystonia-associated gene only recently, more than one hundred rare or private heterozygous single nucleotide variants (SNVs) as well as insertions/deletions (indels) have been identified in this gene, the majority predicted to cause haploinsufficiency." (PMID 34380541, 2021). "DYT28 is a recently identified form of dystonia caused by heterozygous inactivating KMT2B variants." (PMID 34380541, 2021). "To assess this hypothesis, we investigated whether the exomes of dystonia patients had a mutation in some of the KMT2B targets identified thanks to the molecular dissection of KMT2B role during transdifferentiation." (PMID 32596666, 2020). "Summary of KMT2B novel variants identified in three probands with dystonia." (PMID 31338059, 2019). "Fibroblast and CSF protein expression analysis were also used to determine whether KMT2B mutations could impact on other known dystonia-related pathways." (PMID 28188465, 2017). "Among these, KMT2B-related dystonia is increasingly recognized due to its early onset and responsiveness to deep brain stimulation." (PMID 40531829, 2025). "Among the dystonic children, 9 were diagnosed with CP, 3 with pantothenate kinase-associated neurodegeneration (PKAN), 3 with KMT2B, 2 with SLC18A2-related dystonia, 2 with WARS2, and 2 with suspected neurotransmitter disorder." (PMID 40531829, 2025). "By addressing both the distinctive clinical features and the challenges in diagnosis and treatment, this report contributes valuable insights into the spectrum of KMT2B-related dystonia." (PMID 40303543, 2025). "For instance, KMT2B-related dystonia shares several overlapping symptoms with cerebral palsy, which can complicate the diagnostic process." (PMID 40303543, 2025). "The same variant (c.4789C>T), was identified in two unrelated patients, one with typical KMT2B-related dystonia (Patient 25) and another aged 12 years (Patient 50), who had a neurodevelopmental phenotype without dystonia." (PMID 39990802, 2025). "It is already well known that dystonia is a common feature in this syndrome, and is produced, according to some authors, by the haploinsufficiency of the KMT2B gene." (PMID 35205257, 2022). "Recently, heterozygous variants in lysine methyltransferase 2B (KMT2B; MIM *606834), encoding a histone H3 methyltransferase, have been associated with a childhood-onset, progressive and complex form of dystonia named dystonia 28 (DYT28; MIM #617284)." (PMID 34380541, 2021). "Heterozygous variants in lysine methyltransferase 2B (KMT2B), encoding a histone H3 methyltransferase, have been associated with a childhood-onset, progressive and complex form of dystonia (dystonia 28, DYT28)." (PMID 34380541, 2021). "A genetic etiology was identified in 17 patients [eight harboring TOR1A (DYT1), five harboring THAP1 (DYT6), and four harboring KMT2B (DYT28)] while the rest had idiopathic dystonia (n = 16)." (PMID 32322234, 2020). "In this study, we screened KMT2B in a cohort of early-onset Chinese dystonia patients by whole-exome sequencing to expand the current knowledge on this gene." (PMID 31338059, 2019). "Similarly, proper KMT2B functioning is essential for adequate expression of other dystonia-linked genes, such as THAP1 and TOR1A, which were reported to be downregulated in fibroblasts derived from patients with KMT2B pathogenic variants." (PMID 41518464, 2026). "The majority (n=43) were carriers of heterozygous variants in genes linked to dominantly inherited dystonia genes (ATP1A3, GCH1, SGCE, KMT2B, THAP1, TOR1A, and VPS16), while only one carrier of a homozygous PLA2G6 variant and one of compound-heterozygous PTS variants were identified." (PMID 40672488, 2025). "Given the rarity of KMT2B-related dystonia, existing evidence remains limited." (PMID 40303543, 2025). "Within the cohort, we identified nine patients (seven females) with pathogenic mutations in KMT2B, in whom there has been no evolution of dystonia." (PMID 39990802, 2025).
Dystonia (continued). "Notable examples include cases of KMT2B-related dystonia caused by a coding mutation not captured by WES and BCL11B-related dystonia resulting from copy number variants that were difficult to detect using standard exome techniques." (PMID 40722357, 2025). "KMT2B-related dystonia appears refractory to commonly prescribed anti-dystonic agents." (PMID 39990802, 2025). "Since its first description in 2016, approximately one hundred KMT2B genetic variants have been reported with heterogeneous phenotypes, including atypical patterns of dystonia evolution and non-dystonic neurodevelopmental phenotypes." (PMID 38425714, 2024). "KMT2B, encoding a histone H3 lysine 4 (H3K4)-specific N-methyltransferase responsible for posttranslational modification of histones, plays an essential role in the regulation of dystonia." (PMID 37270714, 2024). "In accordance with the scientific literature, we detected potentially relevant variations in known genes previously associated with CD and BSP, such as CIZ1, GNAL, and ANO3, and in other dystonia-related genes, such as KMT2B, VPS16, and KCNN2, for a total of nine patients." (PMID 37445923, 2023). "Haploinsufficiency of KMT2B causes KMT2B-related dystonia as well as a neurodevelopmental (non-dystonic) phenotype." (PMID 36923252, 2023). "We report a new heterozygous mutation in the KMT2B gene as a cause of generalized early-onset dystonia not reported in the literature until the date." (PMID 36122281, 2022). "With the discovery of novel dystonia genes, such as GNAL, ANO3, KCTD17, and KMT2B, these subtypes can now be allocated to the realm of inherited forms of dystonia." (PMID 33604773, 2021). "Of note, the clinical phenotype associated with KMT2B variants is emerging as variable and has been reported to include conditions not manifesting dystonia at all." (PMID 34380541, 2021). "Lysine Methyltransferase-2B (KMT2B) dystonia is a recently described autosomal dominant disorder." (PMID 32546208, 2020). "Our study cohort has further confirmed that a small subgroup of patients with KMT2B mutations may not manifest dystonia (9/53, 17.0% cases)." (PMID 39990802, 2025). "Moreover, given the relatively recent recognition of this KMT2B-subtype, the non-dystonia group may be under-recognized, and could account for a larger proportion of KMT2B-related disorders." (PMID 39990802, 2025). "With the development of sequencing technology, more and more atypical cases with KMT2B mutations have been reported, such as paroxysmal cervical dystonia, or isolated oromandibular dystonia, or global development delay without any evidence of dystonia." (PMID 31338059, 2019). "The most frequently implicated genes included the well‐established isolated and combined dystonia genes VPS16 (n = 17 index patients), THAP1 (n = 14), GCH1 (n = 13), SGCE (n = 12), GNAL (n = 8), and KMT2B (n = 8)." (PMID 40533913, 2025). "We also found some DECIPHER patients carrying a duplication CNV containing the KMT2B gene whose common phenotype was GDD in the absence of dystonia." (PMID 36959829, 2023). "Herein, we describe the early diagnosis of KMT2B-related neurodevelopmental disorder by DNA methylation episignature testing in a 4-year-old patient without features of dystonia at diagnosis, which is reported to develop in more than 80% of KMT2B-related disorder cases." (PMID 38425714, 2024). "Moreover, unlike the other 19q13 microdeletion cases that presented with dystonia, our patient also presented dystonia but, interestingly, without having haploinsufficiency of the KMT2B gene." (PMID 35205257, 2022). "Hence, we may be unable to detect disease-relevant genetic interactions of DYT genes that are likely to generate dystonia through a fundamental role during brain development, such as TOR1A, THAP1 and KMT2B." (PMID 32889528, 2020).
Dystonia (continued). "Pathogenic variants in KMT2B have been associated with childhood-onset Dystonia-28 and Intellectual developmental disorder, autosomal dominant 68 (MRD 68) for cases of neurodevelopmental impairment without dystonia (DYT28; OMIM 617284 and MRD68; OMIM 619934, respectively)." (PMID 38425714, 2024).
leukemia (9 papers, 2014 to 2025). A malignant (clonal) hematologic disorder, involving hematopoietic stem cells and characterized by the presence of primitive or atypical myeloid or lymphoid cells in the bone marrow and the blood. "As far as the role of the wt KMT2B in MLL-r leukemia is concerned, it was found to be crucial in the maintenance of MLL-AF9-induced AML cells." (PMID 33302406, 2020). "KMT2B belongs to the MLL (myeloid/lymphoid or mixed-lineage leukemia) family, and was found to be ubiquitously expressed in adult tissues as well as in solid tumor cell lines, its involvement in human cancer has already been established." (PMID 25405613, 2014). "KMT2B is also involved in regulating global H3K4me3 in leukemia." (PMID 40846851, 2025). "Importantly, the oncogenic function of MLL fusion proteins in leukemia is critically dependent upon their association with the scaffolding protein menin, a partner protein of MLL1 and MLL4 (i.e. KMT2A and KMT2B) in the TrxG COMPASS-like complexes." (PMID 27888797, 2017). "KMT2B is a member of the MLL family, known to be involved in infantile leukemia and tumor cell proliferation." (PMID 27806114, 2016). "Understanding whether the H3K4 trimethylation activity of KMT2B is disturbed in KMT2A-rearranged leukemia, and particularly in context with KMT2A::AFF1 and KMT2A::MLLT3 fusion genes, represents an intriguing next chapter in illuminating the pathobiology of KMT2A-rearranged leukemia." (PMID 39834944, 2024).
breast carcinoma (8 papers, 2015 to 2025). "IL-20 and KMT2B expression were also associated with ERα-positive breast cancer tissues." (PMID 27806114, 2016). "We have revealed an important role for KMT2B in the epigenetic transcriptional regulation of cytokine IL-20, and other ERα-responsive genes, in breast cancer cells." (PMID 27806114, 2016). "To confirm the role of KMT2B in breast cancer, we performed IHC on tissue microarrays to observe the in situ expression of the KMT2B protein." (PMID 27806114, 2016). "We analyzed copy numbers (excluding that of KMT2B, for which data were not available in the cBioPortal database) and mutations of these 51 HMTs compiled from 958 TCGA breast cancer specimens." (PMID 25537518, 2015). "Inhibition of IL-20 and KMT2B may have therapeutic benefits in ERα-positive breast cancer." (PMID 27806114, 2016). "These included several well-known cancer genes or their family members with previously less recognized role in breast cancer—FGFR3, FGFR4, NOTCH3, KMT2B, EP300, FLT4 and FAT1." (PMID 40858906, 2025). "Lysine methyltransferase 2B (KMT2B, also known as MLL2), has been reported to catalyze H3K4me3 on enhancers in breast cancer cells." (PMID 38012744, 2023). "We also analyzed the correlation between copy number and mRNA level of 97 PHFs (excluding those of KDM5D and KMT2B, as their RNA-sequencing data were not available) from TCGA breast cancer specimens." (PMID 28055972, 2017).